ROS1 (ROS proto-oncogene 1, receptor tyrosine kinase)
Diseases named in the same sentence as ROS1 in open-access papers (continued):
Sharing a sentence is not in itself a finding about the gene and the disease.
cancer (continued). "Beyond these stipulations, genomic contexts may confer certain groups as rare cancers even within common cancers (e.g. ROS1 fusions in lung cancer or NTRK fusions in colon cancer) or in an atypical demographic context (e.g. male breast cancers)." (PMID 39083545, 2024). "Currently undergoing clinical evaluation in ALK and ROS1 fusion-positive NSCLC cancers, PF-06463922, a next-generation ROS1/ALK small-molecule inhibitor, exhibits potent inhibition of various oncogenic ROS1 fusion variants and selective activity against a wide range of kinases." (PMID 38655260, 2024). "As a proto‐oncogene, ROS1 is mostly expressed in malignant tumors such as NSCLC." (PMID 38629293, 2024). "However, in addition to the genetic alterations within the ROS1 gene itself, there are extrinsic mechanisms that can affect the activity and response of ROS1-dependent cancers." (PMID 38655260, 2024). "ROS1 partners displayed considerable heterogeneity in different cancer types." (PMID 37584407, 2023). "However, the development of resistance to ROS1 inhibitors remains an urgent focus of clinical research, since the only remaining clinical interventions for ROS1 inhibitor-resistant cancers are chemotherapy or locally ablative therapy." (PMID 37324948, 2023). "While the combination of the analysis of 5′/3′-end RET expression imbalance and variant-specific PCR allowed identification of RET translocations in approximately 2% of consecutive NSCLCs, this estimate approached 120/2361 (5.1%) in EGFR/KRAS/ALK/ROS1/BRAF/MET-negative carcinomas." (PMID 37445709, 2023). "This retrospective review of NSCLC genomics data from the BC Cancer Genomic Lab Oncopanel Dataset summarizes the frequency of actionable driver mutations (EGFR, KRAS G12C, MET Exon 14 skip, ALK fusion, and ROS1 fusion), PDL-1 expression, and treatment wait times among five health authorities." (PMID 36661661, 2022). "N stage cancer patients are significantly less inclined to harbor BRAF, ROS1 and AKT1 mutations." (PMID 36429016, 2022). "A synthetic study has introduced the role of ROS1 in various cancers." (PMID 36589752, 2022). "Crizotinib is an FDA-approved ROS1 inhibitor that could potentially target the FIG-ROS1 fusion and is being used as salvage therapy for cancers." (PMID 34671307, 2021). "For now, 16 genes have been identified as ROS1 fusion partner genes according to Catalogue of Somatic Mutations in Cancer (COSMIC) data bese, and ROS1 arrangements have been observed in 1–2% NSCLC, most of which are adenocarcinomas, female, and never or light smokers." (PMID 34977873, 2021). "NRAS mutations have also been identified as resistance mechanisms using patient-derived cell line models harboring RET and ROS1 gene fusions, further supporting the idea that cancers often develop resistance using a somewhat finite group of oncogenes following TKI treatment." (PMID 34642436, 2021). "Furthermore, the inhibitory activity of gilteritinib against ROS1-rearranged cancer was equivalent to that of crizotinib, the approved TKI for ROS1-rearranged NSCLC." (PMID 33627640, 2021). "In addition to doubling the available cell lines for research on ROS1+ cancers, this patient‐driven project highlights the importance of engaging patients to accelerate cancer research." (PMID 34515408, 2021). "Because the tyrosine kinase domains of ROS1 and NTRK share structural similarity with that of ALK and multiple ALK inhibitors exert inhibitory effects on ROS1 and NTRK kinase activity, we assessed the efficacy of gilteritinib against ROS1 or NTRK fusion using cancer cell lines and Ba/F3 models." (PMID 33627640, 2021). "Admittedly, ROS1 targeted inhibitors, represented by crizotinib, achieved tremendous success in ROS1-fusion cancers especially NSCLC, but actually, rearrangement just accounts for a fairly small proportion of patients, less than 2% in NSCLC, and even lower in other malignancies." (PMID 34221982, 2021).
cancer (continued). "Long-term efforts have been devoted to develop tyrosine kinase inhibitors targeting the continuously activated ROS1 proteins resulted by chromosomal rearrangements, and crizotinib has received approval of the U.S. Food and Drug Administration (FDA) for ROS1-rearranged cancers." (PMID 34221982, 2021). "Preliminary data from ongoing clinical studies assessing novel inhibitor compounds are very promising, and although ROS1-rearranged cancers are relatively rare, new therapies might provide clinicians with treatment suggestions." (PMID 33172113, 2020). "Furthermore, receptor tyrosine kinases (RTKs) found in ROS1-positive cancers are druggable targets and TKIs (such as crizotinib) therefore emerged as promising agents for the treatment of these cancers." (PMID 33172113, 2020). "Moreover, we have generated a ROS1-positive cancer cell line, starting from a NSCLC that arose in a K-RasG12D mouse, that can be serially transplanted into syngeneic mice, offering an additional tool for studying the potential of ROS1 targeting." (PMID 32268572, 2020). "Furthermore, the activation of bypass signalling as a method of crizotinib resistance in ROS1 cancer cells has been described in various studies and identified in approximately 45% of crizotinib-resistant ROS1-rearranged NSCLC malignancies." (PMID 33172113, 2020). "In this guideline, we generically name EGFR mutation, ALK translocation, ROS1 translocation, and BRAF mutation as driver oncogenes that might be the direct cause of cancer evolution." (PMID 31049758, 2019). "ROS1 which belongs to a family of receptor tyrosin kinases (RTKs) plays a vital role in growth and differentiation of normal cells, and in the development and progression of different cancers." (PMID 30791612, 2019). "Five-point-five percent 5.5% of these patients displayed somatic alterations classified as 2b, defined as an approved biomarker in another cancer indication and included ERBB2 amplifications, CDK4 amplifications, BRCA1/2 mutations, BRAFV600E mutation and fusion events involving ROS1 and ALK1." (PMID 29156578, 2017). "In addition, FIG-ROS1, SLC34A2-ROS1, CD74-ROS1, EZR-ROS1, TPM3-ROS1 and SDC4-ROS1 and related variants are recognized as new cancer driver genes and are associated with sensitivity to ROS1 inhibition." (PMID 26802023, 2016). "Here, we review the biology of ALK and ROS1 and their roles in cancer progression." (PMID 26802023, 2016). "That is only a small population of cancer cells carry ROS1 fusion." (PMID 25742289, 2015). "Genetic modifications in other genes, including targeted mutations in BRAF, AKT1, ERBB2 and PIK3CA, as well as ROS1- and RET-involved fusions, may also affect cancer therapy." (PMID 24646369, 2014). "Therefore, we hypothesized that the resistance mechanism of MIG6 depletion could be applicable in ROS1-rearranged cancers." (PMID 37917191, 2023). "In addition, the distribution of ROS1 fusions varies among different types of cancer." (PMID 36589752, 2022). "Exploring ROS1 fusions in different cancers may help identify more precise therapies." (PMID 36589752, 2022). "Additionally, the response of ROS1-positive cancers to immunotherapy appears to be infrequent." (PMID 33172113, 2020). "Similarly, cancer cells were ROS1-positive in the metastatic sites." (PMID 32268572, 2020). "We recently addressed this topic too by evaluating the frequency of an extended panel of cancer-relevant mutations that could have possibly affected the initial response to erlotinib in a consecutive series of EGFRM+/ALK-negative/ROS1-negative advanced NSCLCs." (PMID 31266248, 2019).
cancer (continued). "Preclinical studies showed that ROS1-positive cancer cells, including the G2032R variant, are sensitive to MET/VEGFR2 inhibitor foretinib, strongly suggesting that foretinib could be the drug of choice for ROS1-positive NSCLC." (PMID 24722523, 2014). "This cancer type was selected due to its prevalence, the clinical importance of identifying ALK and ROS1 fusions for targeted therapy, and the need for rapid, cost-effective alternatives to traditional diagnostic methods such as FISH and IHC13–16." (PMID 40739404, 2025). "Based on a meta-analysis of published cohorts, the overall incidences of VTE with ALK, ROS1, EGFR, and wildtype cancers are 41%, 30%, 12%, and 14%, respectively." (PMID 39858040, 2025). "Entrecitinib, an ROS1 tyrosine kinase inhibitor (TKI), is one of the primary therapies for ROS1 fusion-positive cancers." (PMID 39802058, 2025). "A total of 1,501 distinct fusions in at least one of the nine driver genes assessed (ALK, RET, ROS1, NTRK1/2/3, FGFR2, FGFR3, and NRG1) were detected in 1,497 patients for a combined prevalence of 2.2% across the pan-cancer cohort." (PMID 41091579, 2025). "ROS1 rearrangements, present in 1–2% of NSCLC cases, lead to auto-phosphorylation and activation of the MAPK pathway which drives cancer cell proliferation." (PMID 39199633, 2024). "We analyzed 8,805 3’ kinase gene fusions curated from the COSMIC, focusing on the seven most common kinase fusions involving ALK, RET, ROS1, NTRK1, NTRK3, ABL1, and BRAF genes found in various types of cancers." (PMID 38877018, 2024). "ROS1, a member of the RTK family, is a known oncogenic driver in various cancers, particularly lung adenocarcinoma." (PMID 38791529, 2024). "Crizotinib, an anti-cancer medication through inhibiting anaplastic lymphoma kinase (ALK) and c-ros oncogene 1 (ROS1), has already been approved for the treatment of NSCLC." (PMID 36834736, 2023). "Mechanistically, ROS1 inhibitors induce the FAK-YAP-TRX signaling, decreasing oxidative stress-related DNA damage and consequently reducing their anti-cancer effects." (PMID 37324948, 2023). "Several TKIs now have demonstrated activity across cancer types, so called “agnostic” indications, including the TRK inhibitor larotrectinib, the TRK/ROS1 inhibitor entrectinib, and the RET inhibitors selpercatinib and pralsetinib." (PMID 37168365, 2023). "In general, this novel method holds great potential to improve clinically relevant gene fusion detection for higher applicability of modern cancer therapies targeting ALK, ROS1, RET, and other gene fusions." (PMID 37300660, 2023). "Pan-cancer drug target RTK fusions also include the moieties of ALK, ERBB2, FGFR1-4, MET, RET, and ROS1 genes." (PMID 36009413, 2022). "Customized probes were designed to capture exonic regions of 141 genes selected for the panel, which was aimed for the detection of clinically actionable genetic variations in cancer, including KRAS, NRAS, BRAF, ALK, ROS1, KIT and EGFR." (PMID 35446881, 2022). "All four CB results obtained from carcinoma NOS were adequate for ALK, ROS1 and PD‐L1 assessment and molecular profiling." (PMID 35868633, 2022). "All CBs related to carcinoma NOS were adequate for ALK, ROS1 and PD‐L1 assessment and also molecular profiling." (PMID 35868633, 2022). "Two patients received a diagnosis of carcinoma NOS, and all samples were adequate for ALK, ROS1 and TPS PD‐L1 immunohistochemical assessment and molecular profiling." (PMID 35868633, 2022). "Entrectinib is an inhibitor of TRK, ROS1, and ALK, and has been shown to induce rapid and durable anti-cancer responses in NTRK, ROS1, and ALK-fusion tumors." (PMID 35126101, 2021). "In the case of NTRK and ROS1 fusions, the FDA-approved pan-cancer drugs, larotrectinib, and entrectinib are readily available for clinical treatment in these subsets of NPC patients." (PMID 34234122, 2021).
cancer (continued). "Further studies are needed to better characterize the relationship between ROS1-GOPC fusion with the pathogenesis of nasopharyngeal papillary adenocarcinoma and response to TKIs such as crizotinib and lorlatinib toward this carcinoma." (PMID 33546077, 2021). "Further studies are needed to further characterize the relationship between ROS1-GOPC fusion and the pathogenesis of this carcinoma and its response to tyrosine kinase inhibitors in relapsed cases." (PMID 33546077, 2021). "Given their robust oncogenic drive and pharmacologic targetability, kinase fusions have garnered substantial attention as therapeutic targets in cancer, including the noteworthy first fusion to be targeted, BCR-ABL, followed by ALK, ROS1, and NTRK fusions." (PMID 33328556, 2020). "Later on, more targeted drugs have been developed against well-recognized driver kinases activated in cancer due to KGFs, such as those involving ALK, RET, ROS1, NTRK or FGFR39." (PMID 33257674, 2020). "Crizotinib is an ATP-competitive inhibitor targeting ALK/ROS1/c-MET kinases that has been approved by the FDA as a first-line chemical for the treatment of NSCLC and other cancers with ALK rearrangement, ROS1 rearrangement, or aberrant activation of c-MET2-5." (PMID 32792859, 2020). "Remarkable success has been achieved by targeting oncogenic gene fusions including diverse tyrosine kinase inhibitors against fusions involving ALK, ROS1, RET, FGFR1/2/3, and NTRK1/2/3 in non-small-cell lung cancer and across a wide spectrum of cancer types." (PMID 32411236, 2020). "A newer inhibitors, entrectinib (RXDX-101), is a ROS1, Pan-TRK, and ALK inhibitor with activity in multiple molecularly defined cancer indications." (PMID 30930778, 2019). "This analysis identified new contexts for fusion transcripts leading to overexpression of cancer genes located at the fusion 3′ end, such as NUTM1, RSPO2/3, and ROS1." (PMID 31097696, 2019). "We describe the first case of HAS harboring a fusion of ROS1 with GOPC/FIG and review of the role of ROS1 rearrangements in cancer and evidence supporting the use of therapeutics that target ROS1." (PMID 30719217, 2019). "Here, we found fusion genes involving BRAF, NTRK3, ALK, FGFR1, and ROS1, which result in activation of the MEK/ERK pathway in other cancers." (PMID 29654269, 2018). "The strong anti-cancer effects of (S)-crizotinib in inhibiting GC cell growth likely indicate that these cells harbor alterations of ALK, ROS1, and or MET, although their precise genomic profile remains to be determined." (PMID 29855474, 2018). "Next, we used FISH to determine the absolute copy number at loci harboring cancer-relevant genes: ALK, ROS1, MET, BRAF and RET." (PMID 27100738, 2016). "First, drugs that inhibit ALK, ROS1, and RET kinases have marked therapeutic effects on fusion-positive LADCs because the survival and growth of such cancer cells are highly dependent on the kinase activity of fusion proteins." (PMID 26437441, 2015). "We showed that PY136 inhibited cancer cell proliferation by inhibiting the phosphorylation of Tyr136 of the LIX1L protein in vitro and in vivo, and ROS1 phosphorylated LIX1L protein to result in cell proliferation." (PMID 26310847, 2015). "Kinase fusion genes detected across multiple cancer types include RET, NTRK1, NTRK3, ALK, ROS1, FGFR1/2/3, and serine threonine kinases including the RAF family genes BRAF, RAF1, CRAF, and MAST1/2." (PMID 26684754, 2015). "Second, our pipeline was able to recapitulate most known translocation events in cancer (ALK, BRAF, EGFR, FGFR1, 2 and 3, NTRK1, 2 and 3, PDGFRA, PRKCA, RAF1, RET, ROS1)." (PMID 25204415, 2014). "The second subgraph, which contains the largest number of component nodes, has its 95 nodes anchored to the known cancer proteins CTNNB1, APC, PTEN, TP63, MAPK4, MET, RAC1, and ROS1." (PMID 24516372, 2014).
cancer (continued). "Cancer cDNA array studies demonstrated over-expression of TRK-A and ROS1 in a variety of cancers, compared to their respective normal tissue controls." (PMID 24386191, 2013). "GTx-186 efficiently inhibited cancers driven by TRK-A and ROS1 expression and was also exceptional in overcoming inflammatory diseases such as dermatitis." (PMID 24386191, 2013). "The interest in this pathway has gradually increased since the identification of two potent inhibitors, larotrectinib and entrectinib, with a wide spectrum of action and efficacy not only in NTRK altered cancer cells but also in cases where other altered genes are present, such as ALK or ROS1." (PMID 41465387, 2025). "Clinical trials are assessing new ROS1 inhibitors for ALK and ROS1 fusion-positive NSCLC cancers." (PMID 38655260, 2024). "Low expression of thymidylate synthase may explain an increased sensitivity of ALK-, ROS1- and RET-driven cancers to pemetrexed." (PMID 38966170, 2024). "All ALK and ROS1 fusions were detected in adenocarcinomas, and RET fusions were detected mostly in adenocarcinomas (11/12, 91.7%), except in one case of poorly differentiated carcinoma." (PMID 39507756, 2024). "This review further highlights promising targets like mesenchymal-epithelial transition (MET), ROS1, BRAF, and poly(ADP-ribose) polymeras (PARP) in specific cancer subsets, along with ongoing clinical trials that continue to shape the future of targeted therapy." (PMID 37686423, 2023). "ALK inhibition is a known mechanism for inducing apoptosis, and cancer cells (such as non-small-cell lung cancers (NSCLCs) and RMS) are often dependent on ALK and ROS1 function, providing a reasonable rationale for evaluating crizotinib and ceritinib in these cancers." (PMID 37958442, 2023). "Additionally, we discuss emerging targets in specific cancer subsets, such as mesenchymal-epithelial transition (MET), ROS1, BRAF, and poly(ADP-ribose) polymerase (PARP), that hold promise for further advancing targeted therapies." (PMID 37686423, 2023). "We calculated the mutation rate of the ROS1 and PTPRT genes for each cancer type and found them not to be high." (PMID 35197093, 2022). "In conclusion, we characterized the genomic landscape of solid tumor patients with ALK, ROS1, and NTRK fusions and 62 novel fusions were discovered, which may provide more clinically actionable targets for cancer therapy to a great extent." (PMID 35785159, 2022). "Small molecule inhibitors for ALK, ROS1, and NTRK fusions, such as crizotinib, brigatinib, lorlatinib, entrectinib and larotrectinib, have been approved by the US Food and Drug Administration (FDA) for different cancer types." (PMID 35785159, 2022). "In addition to ALK, RET, NTRK1, and ROS1, fusions involving FGFR1/2/3 and NRG1 genes have been reported in NSCLC among other cancers and represent emerging therapeutic targets." (PMID 35328282, 2022). "In addition, gilteritinib was effective against NTRK-rearranged cancers including entrectinib-resistant NTRK1 G667C-mutant and ROS1 fusion-positive cancer." (PMID 33627640, 2021). "This might weaken their efficacy against brain tumors (e.g., brain metastasis and gliomas) that often also include ROS1, ALK, and NTRK fusion-positive cancers." (PMID 34834176, 2021). "The discovery of driver oncogenes with aberrant tyrosine kinase activation, such as ALK, ROS1, RET, or NTRK1 gene rearrangement in cancers, continues to change the therapeutic strategies and treatment regimens accompanied with the development of targeted therapies." (PMID 32871626, 2020). "In this analysis we found only two cases carrying ROS1-GOPC fusions: high grade glioma and cancer of unknown primary." (PMID 30719217, 2019). "The identification of fusion driver oncogenes with aberrant tyrosine kinase activation, such as ALK, ROS1, RET, or NTRK1 rearrangement in cancers, is largely changing therapeutic strategies accompanied with the development of targeted therapies, especially potent TKIs." (PMID 31399568, 2019).